FOXJ2 (forkhead box J2)
Description:
[Isoform FOXJ2.L]: Transcriptional activator. Able to bind to two different type of DNA binding sites. More effective than isoform FOXJ2.S in transcriptional activation. Plays an important role in spermatogenesis, especially in spermatocyte meiosis (By similarity). [Isoform FOXJ2.S]: Transcriptional activator.
Synonyms: FHX
Tractability: PROTAC: ubiquitination databases record sites on it.
Gene: Protein-coding gene on chromosome 12 (8,032,698 to 8,055,522, forward strand). Ensembl gene ENSG00000065970.
Subcellular location: Nucleus
Subcellular location (Human Protein Atlas): Nucleoplasm; Nucleoli fibrillar center
Pathways (Reactome):
Cell-Cell communication: Positive Regulation of CDH1 Gene Transcription
Gene Ontology:
Molecular function: DNA-binding transcription activator activity, RNA polymerase II-specific; identical protein binding; protein binding; RNA polymerase II cis-regulatory region sequence-specific DNA binding; sequence-specific double-stranded DNA binding; DNA-binding transcription factor activity, RNA polymerase II-specific; DNA-binding transcription factor activity; sequence-specific DNA binding
Biological process: negative regulation of angiogenesis; negative regulation of blood vessel endothelial cell differentiation; positive regulation of transcription by RNA polymerase II; positive regulation of vascular associated smooth muscle cell proliferation; male meiosis I; regulation of transcription by RNA polymerase II; spermatogenesis; regulation of DNA-templated transcription
Cellular component: fibrillar center; nucleoplasm; nucleus; chromatin
Genetic constraint (gnomAD): Loss-of-function variants: 18 observed, 67.07 expected, observed/expected ratio (o/e) 0.27, 90% interval 0.18 to 0.4. The upper end of that interval is the gene's LOEUF score, 0.4, which puts it in group 1 of 6, group 1 being the genes least tolerant of losing a copy. Missense variants: 669 observed, 735.82 expected, observed/expected ratio (o/e) 0.91, 90% interval 0.85 to 0.97. Synonymous variants: 273 observed, 269.76 expected, observed/expected ratio (o/e) 1.01, 90% interval 0.92 to 1.12.
Homologues: Orthologues: chimpanzee FOXJ2 (99% identical), macaque FOXJ2 (99% identical), dog FOXJ2 (95% identical), rabbit FOXJ2 (93% identical), guinea pig FOXJ2 (91% identical), rat Foxj2 (90% identical), mouse Foxj2 (90% identical), pig FOXJ2 (90% identical), tropical clawed frog foxj2 (46% identical). Paralogues in human: FOXJ3 (41% identical), FOXD1 (16% identical), FOXK2 (16% identical), FOXD2 (15% identical), FOXD3 (15% identical), FOXA1 (15% identical), FOXC1 (15% identical), FOXM1 (14% identical), FOXA2 (14% identical), FOXC2 (14% identical), FOXK1 (14% identical), FOXD4L1 (14% identical), and 29 more.
Diseases named in the same sentence as FOXJ2 in open-access papers:
FOXJ2 is named in the same sentence as 44 diseases in open-access papers, as found by Europe PMC text mining. Sharing a sentence is not in itself a finding about the gene and the disease. The quoted sentences say what the papers report.
breast carcinoma (4 papers, 2007 to 2021). "Serum FOXJ2-Ab levels, which correlated well with hypertension, were elevated in patients with colorectal carcinoma (P < 0.001) but not in those with esophageal squamous cell carcinoma, gastric cancer, breast cancer, or pancreatic cancer." (PMID 34103026, 2021). "However, it has been reported that FOXJ2 suppresses migration and invasion in extrahepatic cholangiocarcinoma, hepatocellular carcinoma, glioma, and breast cancer." (PMID 34103026, 2021). "Breast cancer cell migration and invasion may be inhibited if FOXJ2 expression is increased." (PMID 34992653, 2021). "FOXJ2 has been suggested to function as a tumor suppressor gene in breast cancer cells, glioma cells, cholangiocarcinoma cells, HCC cells, and non–small-cell lung cancer, and low expression levels of FOXJ2 indicates poor prognosis of cancer patients." (PMID 30335765, 2018). "Another example relevant for breast cancer is the hsa-miR-17-5p/EREG pair of miRNA and predicted target gene that putatively form FFLs with E2F1, EGR2, FOXJ2 and RUNX1." (PMID 17971223, 2007).
hepatocellular carcinoma (3 papers, 2018 to 2022). A malignant tumor that arises from hepatocytes. "And ARHGAP9/Forkhead Box J2 (FOXJ2) inhibits cell migration and invasion during the development of hepatocellular carcinoma through induction of E-cadherin transcription." (PMID 35040754, 2022).
atherosclerosis (2 papers, 2021 to 2024). A disease characterized by the build-up of fatty material and calcium deposition in the arterial wall resulting in partial or complete occlusion of the arterial lumen. "Serum antibody levels of DIDO1, FOXJ2, and CPSF2 are useful in predicting the onset of atherosclerosis-related AIS caused by kidney failure, hypertension, and DM, respectively." (PMID 34103026, 2021). "For instance, the antigenic proteins of other atherosclerosis autoantibody markers, DIDO1-Abs, CPSF2-Abs, and FOXJ2-Abs, were highly expressed in the carotid atherosclerotic plaques." (PMID 38732153, 2024). "Thus, FOXJ2-Ab may be associated with kidney failure and atherosclerosis, but it does not primarily reflect DM." (PMID 34103026, 2021).
Sepsis (2 papers, 2022 to 2025). Sepsis is defined as life-threatening organ dysfunction caused by a dysregulated host response to infection. "In sepsis, impaired function of Foxj2 may lead to uncontrolled Tak1 signaling, which in turn drives “cytokine storms” and chronic inflammation." (PMID 41498035, 2025). "The present findings indicated that Foxj2 is crucial in mitigating macrophage inflammation induced by LPS and might be considered a target for treating sepsis and other inflammatory diseases." (PMID 41498035, 2025).
Alzheimer disease (1 paper, 2018). A progressive, neurodegenerative disease characterized by loss of function and death of nerve cells in several areas of the brain leading to loss of cognitive function such as memory and language. "Other transcription factors had wide-scale roles in different processes, e.g., FoxJ2 is an important regulator of dopaminergic neurons and Oct1 (Pou2f1) polymorphisms associated with Alzheimer’s disease." (PMID 30559663, 2018).
autism (1 paper, 2010). Persistent deficits in social interaction and communication and interaction as well as a markedly restricted repertoire of activity and interest as well as repetitive patterns of behavior. "The six candidate genes sequenced, CNTN1, FOXJ2, GRIN2B, NAB2, NELL2 and SRGAP1, were selected based on their putative functions, and their relationships to genes potentially involved in the pathology of language impairments, auditory processing deficits, autism and dyslexia." (PMID 20345892, 2010).
cerebral infarction (1 paper, 2021). An ischemic condition of the brain, producing a persistent focal neurological deficit in the area of distribution of the cerebral arteries. "Likewise, the antibody levels of the DIDO1, FOXJ2, and CPSF2 peptides were positively correlated with a risk of cerebral infarction: odds ratios (95% CIs) of the highest quartile were 2.66 (1.43–4.95), 2.24 (1.27–3.95), and 2.41 (1.33–4.37), respectively." (PMID 34103026, 2021).
collagen disease (1 paper, 2021). "It is possible that DIDO1-Ab and FOXJ2-Ab are discriminant in the case of AIS of which one of the causes is a collagen disease." (PMID 34103026, 2021).
colorectal carcinoma (1 paper, 2021). A malignant epithelial neoplasm that arises from the colon or rectum and invades through the muscularis mucosa into the submucosa. "Thus, FOXJ2 can promote or suppress malignancy depending on cancer type, which may account for the colorectal carcinoma-selective association of FOXJ2-Abs." (PMID 34103026, 2021). "Serum FOXJ2-Ab levels were elevated in patients with TIA, AIS, cCI, AMI, DM, CKD, colorectal carcinoma, rheumatoid arthritis, and SLE compared with in HDs." (PMID 34103026, 2021). "However, serum FOXJ2-Ab levels were significantly higher in patients with colorectal carcinoma but not in those with other types of cancer than in HDs." (PMID 34103026, 2021).
dyslipidemia (1 paper, 2021). "Serum FOXJ2-Ab levels showed similar results, except that they were not correlated with dyslipidemia." (PMID 34103026, 2021).
Hypertension (1 paper, 2021). The presence of chronic increased pressure in the systemic arterial system. "Although the present study suggests kidney failure-associated DIDO1-Ab, hypertension-related FOXJ2-Ab, and DM-related CPSF2-Ab markers as risk factors of AIS, further study using the increasing number of specimens is needed to verify the suggestion." (PMID 34103026, 2021). "Receiver operating characteristic curves showed that serum DIDO1 antibody levels were highly associated with CKD, and correlation analysis revealed that serum anti-FOXJ2 antibody levels were associated with hypertension." (PMID 34103026, 2021). "Serum DIDO1-Ab, FOXJ2-Ab, and CPSF2-Ab appear to be useful for diagnosing AIS and may originate from kidney disease, hypertension, and DM, respectively." (PMID 34103026, 2021). "Serum FOXJ2-Ab levels correlated well with hypertension and were elevated in patients with CTEPH and PAH, suggesting that these levels reflect systemic arterial hypertension and can differentiate hypertension-related diseases." (PMID 34103026, 2021).
male infertility (1 paper, 2022). The inability of the male to effect fertilization of an ovum after a specified period of unprotected intercourse. "Foxj2 overexpression in mouse testes led to spermatogenesis failure, which started at the initiation of meiosis, and resulted in male infertility." (PMID 35908066, 2022). "Our results suggested that Foxj2 overexpression in the germ cells of mouse testes affects chaperone-mediated autophagy by upregulating LAMP2A, leading to spermatogenesis failure at the initiation of meiosis, thus resulting in male infertility." (PMID 35908066, 2022). "In summary, our data showed that overexpression of Foxj2 in the germ cells of mouse testis might affect CMA by upregulating Lamp2a, leading to a failure of spermatogenesis, starting at the initiation of meiosis, and resulting in male infertility." (PMID 35908066, 2022).
nasopharyngeal carcinoma (1 paper, 2021). A carcinoma arising from the nasopharyngeal epithelium. "FOXJ2 overexpression is associated with poor prognosis, progression, and metastasis in nasopharyngeal carcinoma." (PMID 34103026, 2021).
nonalcoholic fatty liver disease (1 paper, 2025). "Unexpectedly, it was observed a decline in Foxj2 mRNA expression levels in the adipose tissue of mice with obesity induced by a high‐fat diet (HFD), as well as in the livers of mice with nonalcoholic fatty liver disease (NAFLD) induced by HFD." (PMID 41498035, 2025).
non–small-cell lung cancer (1 paper, 2018). A group of at least three distinct histological types of lung cancer, including non-small cell squamous cell carcinoma, adenocarcinoma, and large cell carcinoma. "It was reported that FOXJ2 expression was down-regulated by transforming growth factor (TGF-β1) in non–small-cell lung cancer." (PMID 30335765, 2018).
prostate carcinoma (1 paper, 2017). A carcinoma that arises from epithelial cells of the prostate gland. "Moreover, 8 of these TFs (FOXJ2, GATA6, NFE2L1, NFIL3, PRRX2, TEF, EBF2 and ZBTB18) were found to be differentially expressed in this study making them not only candidate biomarkers of prostate cancer but also potential therapeutic targets." (PMID 28380430, 2017).
rheumatoid arthritis (1 paper, 2021). A chronic, systemic autoimmune disorder characterized by inflammation in the synovial membranes and articular surfaces. "Serum DIDO1-Ab and FOXJ2-Ab levels were significantly associated with rheumatoid arthritis and SLE but not with Sjögren’s syndrome or ulcerative colitis." (PMID 34103026, 2021). "Serum DIDO1-Ab and FOXJ2-Ab levels were significantly higher in patients with rheumatoid arthritis and SLE (but not in those with Sjögren’s syndrome or ulcerative colitis) than in HDs." (PMID 34103026, 2021).
synovial sarcoma (1 paper, 2016). "In total, a group of 42 cases are discovered with MEF2D rearranged to BCL9, CSF1R, DAZAP1 (DAZ (deleted in azoospermia)-associated protein 1), HNRNPUL1 (heterogeneous nuclear ribonucleoprotein U-like 1), SS18 (synovial sarcoma translocation, chromosome 18) or FOXJ2 (Forkhead Box J2)." (PMID 27824051, 2016).
cancer (10 papers, 2010 to 2024). A tumor composed of atypical neoplastic, often pleomorphic cells that invade other tissues. "TGF-β1 treatment did not affect FOXJ2 expression in SK-Hep1 and HepG2 cells, suggesting that various mechanisms of FOXJ2 down-regulation were involved in different types of cancers." (PMID 30335765, 2018). "Furthermore, miR-197-3p directly regulates other genes implicated in trastuzumab resistance, including FOXJ2, MTHFD1, RAN, TUSC2, and FUS1, though their specific roles in drug resistance and cancer progression require further investigation." (PMID 38534787, 2024). "Additionally, even though we can now infer that the FOX co‐expression relationships are globally disrupted in cancer tissues, it is still unclear how the centric FOX regulators shifted from normal (FOXN3 and FOXJ2) to cancer (FOXL1 and FOXD4L)." (PMID 37401400, 2023). "However, whether FOXJ2 can regulate tumor cell metabolism to inhibit cancer progression remains unknown." (PMID 30335765, 2018). "Among these candidates, six genes (RhoGDI1, ALCAM, FOXJ2, FOXO3, NDRG2 and SOX11) were involved in the suppression of cancer metastasis." (PMID 26460549, 2015). "Six multiple interacting TFs were found to have common functions between immune systems and cancer tissues, including CEBPGAMMA:NKX25:PLZF, CEBPGAMMA:PAX4:PLZF, CP2:NFY:PAX4, FOXJ2:PAX4:POU3F2, CEBPGAMMA:PAX4:PLZF, and FOXJ2:HNF3:PAX4." (PMID 20085649, 2010).
tumor (4 papers, 2018 to 2023). "To further define the relationship between FOXJ2 expression and HCC malignancy, we examined FOXJ2 expression in 69 pairs of tumor tissues and peritumoral tissues from HCC patients." (PMID 30335765, 2018). "Our findings uncover a new mechanism that forkhead box protein J2 (FOXJ2)–up-regulated PGM1 expression inhibits tumor cell glycolysis, thereby impairing HCC growth." (PMID 30335765, 2018). "In line with the findings in other types of tumor cells, we reported here that ectopic expression of FOXJ2 remarkably repressed the migration and invasion of HCC cells." (PMID 30206221, 2018). "Semiquantitative analyses of IHC staining of these tissues showed that FOXJ2 expression was dramatically decreased in HCC tumor tissues compared to paired peritumoral tissues." (PMID 30335765, 2018). "Glucose, lactate, and glycogen assays showed that FOXJ2 depletion enhanced glucose consumption and lactate production but reduced glycogen content of tumor cells." (PMID 30335765, 2018). "FOXJ2 overexpression inhibited glucose consumption and lactate production in tumor cells, which was reversed by PGM1 depletion." (PMID 30335765, 2018). "We further overexpressed PGM1 in HepG2 cells and found that the proliferation of HepG2 cells could also be inhibited by PGM1 overexpression, which is similar to SK-Hep1 cells, suggesting that PGM1 is downstream of FOXJ2 and required for FOXJ2-inhibited tumor cell proliferation." (PMID 30335765, 2018). "Consistently, FOXJ2 overexpression inhibited the colonies formation, and PGM1 depletion almost completely abrogated such phenotypes of tumor cells." (PMID 30335765, 2018). "Taken together, these results demonstrate that FOXJ2-dependent PGM1 up-regulation shunt glycolysis to glycogenesis, thereby decreasing the glycolytic intermediates for tumor cell proliferation and HCC development." (PMID 30335765, 2018). "Here, we show that FOXJ2 regulates glucose trafficking between glycolysis and glycogen metabolism by increasing PGM1 expression to inhibit tumor cell glycolysis and proliferation." (PMID 30335765, 2018). "The weights of dissected tumors showed that FOXJ2 overexpression greatly impaired tumor growth, while PGM1 depletion almost completely rescued the tumor growth inhibited by FOXJ2 overexpression." (PMID 30335765, 2018). "Among the predicted transcription factors, FOXJ2 was the first transcriptional factor that might regulate PGM1 expression and was also reported to suppress tumor growth." (PMID 30335765, 2018).
infection (2 papers, 2025). The state of being infected such as from the introduction of a foreign agent such as serum, vaccine, antigenic substance or organism. "Ad‐Foxj2 infection significantly increased Foxj2 expression in macrophages." (PMID 41498035, 2025). "This function of Foxj2 may represent a crucial “brake” mechanism in vivo, which prevents excessive activation of the immune system when responding to infections, thereby avoiding damage to host tissues." (PMID 41498035, 2025). "GM-2 and GM-3 were predominantly associated with columnar epithelial responses and included regulators such as ATF2, CDX2, FOXJ2, and AHR, with infection-induced up-regulation of TFs such as SPI1, ESRRA, RFX1, and RARA." (PMID 41042872, 2025).
FOXJ2 also shares sentences with these, for which no sentence is quoted: autoimmune disease (2 papers); glioma (2); leukemia (2); acute myocardial infarction (1); asthma (1); cardiomyopathy (1); cholangiocarcinoma (1); diabetes (1); dyslexia (1); Endotoxemia (1); esophageal squamous cell carcinoma (1); gastric cancer (1); ischemic stroke (1); kidney disease (1); kidney failure (1); Obesity (1); osteosarcoma (1); pancreatic cancer (1); pulmonary diseases (1); Sjögren’s syndrome (1); Thrombocytopenia (1); Thrombosis (1); ulcerative colitis (1).